TRPA1 (transient receptor potential cation channel subfamily A member 1)
Diseases named in the same sentence as TRPA1 in open-access papers (continued):
Sharing a sentence is not in itself a finding about the gene and the disease.
Arthritis (continued). "Because CD4+ T cells play a key role in the development of serum-transfer arthritis, T cell-mediated TRPA1-dependent effects cannot be included." (PMID 34768891, 2021). "The finding is of particular interest because it reveals that the recently recognized inducible expression of TRPA1 in human osteoarthritic chondrocytes is involved in increased IL-6 production, characteristic for the pathogenesis of arthritis." (PMID 33374841, 2020). "In many studies using monoiodoacetate and CFA models of arthritis, genetic depletion of TRPA1 or antagonist inhibition, have resulted in significant reduction in cold and mechanical hypersensitivity." (PMID 33193423, 2020). "The present study aims to investigate TRPA1-mediated effects of sulfide donor GYY4137 in K/BxN serum-transfer arthritis, a rodent model of rheumatoid arthritis." (PMID 31551776, 2019). "These previous data are in concordance with our present results: TRPA1 WT mice showed milder mechanical hyperalgesia, arthritis score, and cartilage damage in response to GYY4137." (PMID 31551776, 2019). "The present study was intended to investigate the role of sulfide and TRPA1 channels in the murine K/BxN arthritis model." (PMID 31551776, 2019). "The score of TRPA1 WT vehicle-treated mice undergoing arthritis was higher on day 5 than that of their GYY4137-treated counterparts (7.97 ± 0.66 vs. 5.58 ± 0.67)." (PMID 31551776, 2019). "Alternatively, the slow-releasing sulfide donor ameliorated hyperalgesia, arthritis score, and histological cartilage destruction in TRPA1 WT animals." (PMID 31551776, 2019). "The difference between GYY4137-treated TRPA1 WT and KO animals with serum-transfer arthritis stresses the beneficial effect of the drug in WT mice (5.58 ± 0.67 vs. 8.43 ± 0.51)." (PMID 31551776, 2019). "Considering the efficacy of anti-TNFα agents in the treatment of RA, the fact that TRPA1 appears to be downstream of TNFα in the pathology of arthritis positions it as a potentially important drug target." (PMID 30326593, 2018). "Numerous studies have found that antagonism of TRPA1 normalizes the mechanical hypersensitivity observed after arthritis induction." (PMID 30326593, 2018). "Collectively, these findings demonstrate that TRPA1 is an integral component within the pathogenesis of multiple types of arthritis." (PMID 30326593, 2018). "Cumulatively, however, the evidence supporting a central role for TRPA1 in the pain component of various types of arthritis is quite strong." (PMID 30326593, 2018). "In the CFA and MIA models of arthritis of the knee, the TRPA1 antagonists HC-030031 and AP-18 relieved behavioral sensitization via elevation of mechanical withdrawal thresholds and normalization of weight-bearing between the arthritic and healthy hind-legs." (PMID 30326593, 2018). "In support of a role for TRPA1 in edema promotion, Fernandes and colleagues observed increases in blood flow to the knee in an adjuvant-induced arthritis model, which was prevented by antagonism or genetic knockout of TRPA1." (PMID 30326593, 2018). "While TRPV1 has been more frequently studied in relation to arthritis pathogenesis, there is ample evidence of a role for TRPA1 in models of OA, RA, and gout as well." (PMID 30326593, 2018). "Since only few data are available about the role of TRPA1 in arthritis and related pain, we investigated its involvement in inflammation models of different mechanisms." (PMID 26746673, 2016). "We show for the first time that after this acute exposure, bilateral pain sensitivity occurs in the knee joints of cold-exposed arthritic mice 2 weeks after induction of arthritis, and that this is dependent on the cold sensor, TRPA1." (PMID 26754745, 2016). "Semiquantitative scoring of composite arthritic changes in CFA-injected tibiotarsal joints found the severity of arthritis was significantly decreased in KO animals (WT ipsilateral joint: 4.4 ± 0.19 vs. TRPA1 KO ipsilateral joint: 2.63 ± 0.43)." (PMID 26746673, 2016).
Arthritis (continued). "Besides, oxidative stress generated during gout arthritis can directly activate TRPA1 in sensory neurons to trigger pain in gout model mice." (PMID 38627393, 2024). "TiO2-induced arthritis also enhanced the activation of TRPA1+ neurons." (PMID 36677929, 2023). "Genetic ablation or pharmacological inhibition of TRPA1 reduced mechanical hypersensitivity of gout model mice, suggesting ROS may act upon TRPA1 channel to produce gout arthritis pain." (PMID 37464384, 2023). "In the long run, however, TRPA1 activation might initiate antihyperalgesic and anti-inflammatory processes in serum-transfer arthritis, as suggested by our previous data." (PMID 35745590, 2022). "TRPA1 is considered to be a potential target for relieving arthritis pain." (PMID 36278189, 2022). "The role of TRPA1 in serum-transfer arthritis was examined by the use of genetically modified mice." (PMID 35745590, 2022). "We used two models here in order to confirm the relevance of TRPA1 in TMD-induced pain/arthritis." (PMID 34832855, 2021). "Arthritis score was lowered by GYY4137 in TRPA1 wild-type animals." (PMID 31551776, 2019). "In addition to TNFα and IL-1β, multiple reports have also shown that ROS are elevated in models of arthritis, which are known to be activators of TRPA1." (PMID 30326593, 2018). "Although it is unclear what underlies these opposing findings, part of the mechanism through which TRPA1 may contribute to edema and joint destruction during arthritis is by triggering the release of inflammatory compounds via neurogenic inflammation." (PMID 30326593, 2018). "Furthermore, genetic deletion of TRPA1 also normalized mechanical withdrawal thresholds and weight-bearing in models of arthritis and gout." (PMID 30326593, 2018). "Interestingly, Garrison and Stucky also examined the contribution of TRPA1 to adjuvant-induced arthritis, but within the context of aging by using geriatric (>18-month-old) mice." (PMID 30326593, 2018). "We have previously demonstrated a role for TRPA1 in the secondary mechanical hyperalgesia associated with CFA-induced mono-arthritis, but until now no study has assessed a role for TRPA1 in arthritic pain exacerbation caused by environmental cold." (PMID 26754745, 2016). "The variability in pain thresholds was greater in TRPA1 WT mice than KO mice 2 weeks after arthritis induction, and may be indicative of increased stress from the handling and restraint necessary for pressure application measurement." (PMID 26754745, 2016). "The present results together with those reported by Ferreira’s and Geppetti’s groups show that TRPA1 mediates joint pain in a mouse model of MSU crystal-induced arthritis adding MSU crystals into the list of painful compounds mediating their effects through indirect activation of TRPA1 channels." (PMID 25658427, 2015). "Therefore, to further explore the neuronal mechanism involved in the model and the role of LXA4, we investigated whether LXA4 modulates TRPA1 channels in TiO2-induced arthritis." (PMID 37388729, 2023). "Thus, positive modulators of TRPA1, such as the peptide Ms 9a-1, could be considered as pharmacological agents for the treatment of arthritis symptoms." (PMID 38132938, 2023). "In addition, TRPA1 inhibitors are likely to have analgesic effects on arthritis pain." (PMID 33374841, 2020). "Potentiating TRPA1 by the peptide Ms 9a-1 produced significant analgesic and anti-inflammatory effects in MIA-induced arthritis." (PMID 38132938, 2023). "Nevertheless, knockout of the TRPA1 gene and inhibitors of TRPA1 reduce the development of inflammation and pain response in MIA-induced arthritis." (PMID 38132938, 2023). "One study showed that TRPA1 played a key role in both thermal and mechanical pain in CFA-induced arthritis." (PMID 36926330, 2023).
Arthritis (continued). "Inhibition of TRPA1 in RA synovial fibroblasts by cannabidiol reduces cell viability, proliferation, and cytokine production, showing that TRPA1 possesses anti-arthritic activity and may ameliorate arthritis via targeting synovial fibroblasts under inflammatory conditions." (PMID 35562920, 2022). "Although the TRPA1 and TRPV1 channels have received the greatest attention for their role in arthritis-related models, several other TRP channels have also been studied in this context." (PMID 30326593, 2018). "Both preclinical and clinical data strongly support a role for various TRP channels, especially TRPA1 and TRPV1, in arthritis pain and pathogenesis." (PMID 30326593, 2018). "We examined mRNA expression levels of TRPA1, TAC-1 and CGRP from joint tissues in mice maintained at RT or exposed to cold, 2 weeks after arthritis induction, in order to detect the start of any potential changes caused by acute cold exposure." (PMID 26754745, 2016). "in TRPA1-induced paw inflammation and FCA-induced arthritis." (PMID 36364420, 2022). "The application of a sulphide donor, GYY4137, protects against serum-transfer induced arthritis in WT mice but not in Trpa1-/- mice." (PMID 34768891, 2021). "It was shown that the application of the sulphide donor, GYY4137, in a rodent serum-transfer arthritis model was able to ameliorate the arthritic symptoms in WT mice but not in Trpa1 KO mice." (PMID 34768891, 2021). "Neither GYY4137 nor TRPA1 KO genotype influenced arthritis score in mice injected with control BxN serum." (PMID 31551776, 2019). "According to our data, the protective effect of GYY4137 is mediated by TRPA1, while detrimental actions are independent of the ion channel in the K/BxN serum-transfer arthritis model in mice." (PMID 31551776, 2019). "Furthermore, we presented the first evidence that TRPA1 is involved in the early neutrophil activation and late plasma extravasation in the CFA arthritis model." (PMID 26746673, 2016). "Furthermore, none of the positive modulators of TRPA1 have been tested in the model of MIA-induced arthritis before." (PMID 38132938, 2023). "Although the extent of the TRPA1 channel contribution to arthritis is not conclusive, the current evidence shows the potential for further study to understand and potentially target TRPA1 as an arthritis therapy." (PMID 33193423, 2020). "The protective effect of sulfide in the K/BxN serum-transfer arthritis model might be mediated by non-neuronal TRPA1 expressed on immune and inflammatory cells." (PMID 31551776, 2019). "Based on a literature search, follow-up studies on auranofin and its effects on TRPA1 in in vivo systems have not yet been performed, and no additional manuscripts examining TRPA1 agonists for the treatment of arthritis could be identified." (PMID 30326593, 2018). "Therefore, inhibition of only TRPV1 or TRPA1 could be not enough for efficient alleviation of arthritis pain." (PMID 38132938, 2023). "In concert with our previous findings in the K/BxN serum-transfer arthritis model, DMTS-treated arthritic TRPA1 WT animals did not exhibit elevated cartilage destruction compared to nonarthritic ones, whereas TRPA1 KO mice did." (PMID 35745590, 2022). "Mono-arthritis was induced by unilateral intra-articular injection of complete Freund’s adjuvant (CFA) in CD1 mice, and in mice either lacking TRPA1 (TRPA1 KO) or respective wildtypes (WT)." (PMID 26754745, 2016). "In addition, TRPA1 plays an important role in noxious mechanosensation in normal, inflamed and osteoarthritic models, and we have observed a sustained mechanical hyperalgesia in wild-type (WT) but not TRPA1 knockout (KO) mice with CFA-induced mono-arthritis." (PMID 26754745, 2016).
osteoarthritis (26 papers, 2016 to 2026). A noninflammatory degenerative joint disease occurring chiefly in older persons, characterized by degeneration of the articular cartilage, hypertrophy of bone at the margins and changes in the synovial membrane. "Recently, the activation of transient receptor potential ankyrin 1 (TRPA1) was claimed to be a risk factor in osteoarthritis by causing inflammation and extracellular matrix degradation." (PMID 37006615, 2023). "However, AITC is also associated with reduced inflammation in diseases such as osteoarthritis and inflammatory bowel disease, and like SF, this was conferred through the activation of TRPA1, ERK signaling, and the inhibition of monocyte MCP-1." (PMID 39770075, 2024). "Transient Receptor Potential Ankyrin 1 (TRPA1) is implicated in osteoarthritis." (PMID 35600853, 2022). "Future research should focus on validating these findings in osteoarthritis (OA) models and investigating the long-term effects of TRPA1 modulation on cartilage health and OA progression." (PMID 40143111, 2025). "This suggests that TRPA1 plays a dual role in chondrocyte physiology, integrating inflammatory and biomechanical pathways during osteoarthritis progression." (PMID 40143111, 2025). "A major transient receptor potential cation channel, known as transient receptor potential ankyrin 1 (TRPA1), was found to alleviate joint pain and cartilage degeneration in osteoarthritis." (PMID 39191723, 2024). "TRPA1 has been found to alleviate acute inflammation, joint pain, and cartilage degeneration in osteoarthritis." (PMID 39191723, 2024). "Knockout of the TRPA1 gene significantly reduces symptoms of OA in a monosodium iodoacetate (MIA)-induced model of osteoarthritis in mice." (PMID 38132938, 2023). "For example, TRPA1 antagonists decrease the response of sensory neurons to noxious mechanical stimulation in inflammatory conditions, trauma, or osteoarthritis." (PMID 35877758, 2022). "We have recently shown that in monosodium iodoacetate (MIA)-induced experimental osteoarthritis, TRPA1 activation has a role in mediating inflammation, cartilage degradation and joint pain." (PMID 33374841, 2020). "We have also shown TRPA1 to mediate inflammation, pain, and cartilage degeneration in experimental osteoarthritis." (PMID 33374841, 2020). "Recently, TRPA1 was shown to be functionally expressed in primary human osteoarthritic chondrocytes that possibly explains some of the symptoms of osteoarthritis and provides a potential drug treatment target." (PMID 30388732, 2018). "TRPA1 has an important role in chronic arthritis/osteoarthritis and related pain behaviours in the mouse." (PMID 26746673, 2016). "Due to its mechanosensitive property, we speculated that the role of TRPA1 activation during osteoarthritis is matrix stiffness-dependent." (PMID 37006615, 2023). "We showed recently that TRPA1 mediates cartilage degradation and joint pain in the MIA-model of osteoarthritis (OA) suggesting a hitherto unknown role for TRPA1 in OA." (PMID 27515912, 2016). "TRPA1 activation leads to an increase in intracellular calcium and a rapid increase in cellular melanin content in melanocytes, as well as the activation of the apoptosis pathway in chondrocytes, which represents a central feature in the progression of osteoarthritis." (PMID 33076385, 2020). "In primary human osteoarthritis fibroblast-like synoviocytes, LPS stimulation leads to increased expression of TRP ankyrin 1 (TRPA1), enhanced TRPA1-mediated Ca2+ influx, and synthesis of pro-inflammatory factors." (PMID 34507301, 2021). "In addition, TRPA1 has been found to contribute to many preclinical models of inflammatory diseases such as allergic contact dermatitis, ovalbumin-induced allergic inflammation, carrageenan-induced acute inflammation, gout, osteoarthritis and inflammatory bowel disease." (PMID 33805042, 2021).
osteoarthritis (continued). "In animal models both TRPV1 and TRPA1 activation results in increased release of TNF-α, a pro-inflammatory cytokine important for the development of osteoarthritis." (PMID 27854251, 2016). "Very recently we found that TRPA1 has a role in mediating acute inflammation, cartilage destruction, and joint pain in monosodium iodoacetate (MIA)-induced inflammation and osteoarthritis in the mouse." (PMID 27515912, 2016). "Ms 9a-1 significantly potentiates agonist-induced currents of TRPA1 in vitro, but intravenous or subcutaneous injection of Ms 9a-1 (0.1–0.3 mg/kg) reduces pain, inflammation, and hyperalgesia in different models of pain, including MIA-induced osteoarthritis." (PMID 38203538, 2023). "The exception was represented by patient 6, in whom the expression of TRPV4 and TRPM8 channels was similar to control tissue and TRPA1, TRPV1, and TRPV2 were expressed, although at a lower level, also in the tissue used as control (probably due to an initial degree of osteoarthritis in this tissue)." (PMID 32955611, 2021). "Pharmacological or genetic TRPA1 block has attenuated not only hypersensitivity but also inflammation induced by osteoarthritis, although not in all experimental conditions." (PMID 30388732, 2018). "In osteoarthritis models, both TRPV1 and TRPA1 have been shown to play an important role." (PMID 27854251, 2016). "In animals with experimental osteoarthritis, blocking pharmacologically TRPA1 attenuated mechanical hypersensitivity in nociceptive neurons of the spinal dorsal horn, while TRPA1 block did not attenuate sustained pain as revealed by a conditioned place preference test." (PMID 30388732, 2018).